YTHDF1 (YTH N6-methyladenosine RNA binding protein F1)
Diseases named in the same sentence as YTHDF1 in open-access papers (continued):
Sharing a sentence is not in itself a finding about the gene and the disease.
gastric cancer (51 papers, 2019 to 2026). A primary or metastatic malignant neoplasm involving the stomach. "As a result, the potential role of YTHDF1 in modulating host gene expression in EBV-associated gastric cancer remains largely unexplored." (PMID 41472023, 2025). "The RNA N6‐methyladenosine‐binding protein YTHDF1 is overexpressed in gastric cancer tissues and associates with the suppression of cancer immunity." (PMID 39587835, 2025). "This leads to an elevation in a shorter variant of the YTHDF1 transcript, which has the capacity to invigorate the proliferation and migratory capabilities of gastric cancer cells." (PMID 40588654, 2025). "YTHDF1 was found to have mutation in nearly 7% of gastric cancer patients, and YTHDF1 overexpression was related to poor overall survival." (PMID 36707507, 2023). "A high expression of YTHDF1 was associated with more aggressive tumor progression and poor overall survival of patients with gastric cancers." (PMID 36835633, 2023). "For instance, YTHDF1 was overexpressed in gastric cancer, and YTHDF1 deficiency impaired gastric cancer progression and metastasis." (PMID 36439881, 2022). "In gastric cancer, elevated YTHDF1 has been associated with tumor growth and immune evasion." (PMID 41472023, 2025). "Similarly, in gastric cancer, mutated YTHDF1 enhances the translation of FZD7 to activate the Wnt-β-catenin pathway to promote gastric cancer cell proliferation and tumorigenesis." (PMID 33795663, 2021). "High expression of YTHDF1 was associated with poor overall survival in gastric cancer patients." (PMID 33928028, 2021). "Tong Liu found that YTHDF1 was obviously correlated to high-risk subtype of gastric cancer patients, and used as the biomarker for early diagnosis with high specificity and sensitivity(AUC = 0.986), which suggested that YTHDF1 showed a perfect diagnostic ability in gastric cancer." (PMID 36707507, 2023). "YTHDF1 mutations occur in approximately 7% of gastric cancer (GC) patients, and high expression of YTHDF1 is correlated with high-risk progression and poor prognosis in patients." (PMID 36999016, 2023). "In conclusion, our study reveals a novel epitranscriptomic mechanism through which EBV promotes gastric cancer, involving miRNA-mediated suppression of YTHDF1 and selective hypomethylation of TSC22D1 mRNA." (PMID 41472023, 2025). "Flow cytometric analysis following 7-AAD and Annexin V staining showed that YTHDF1 overexpression significantly reduced apoptosis in EBV-positive gastric cancer cells." (PMID 41472023, 2025). "To investigate the functional role of YTHDF1 in gastric cancer, we designed two independent siRNAs targeting different regions of YTHDF1 mRNA." (PMID 41472023, 2025). "Together, these results indicate that EBV infection suppresses YTHDF1 expression in gastric cancer, at least in part through regulation by EBV BART miRNAs." (PMID 41472023, 2025). "Together, these findings indicate that YTHDF1 acts as a critical regulator that promotes the malignant phenotype of gastric cancer by enhancing cell proliferation and migration." (PMID 41472023, 2025). "Inhibition of YTHDF1 can reduce tumor incidence and suppress gastric cancer (GC) cell proliferation both in vitro and in vivo." (PMID 40271153, 2025). "The acetylated SRSF2 subsequently binds to YTHDF1, enhancing its expression and thereby promoting the proliferation and migration of gastric cancer cells." (PMID 40211955, 2025). "RNA sequencing and microarray analyses demonstrated that EBV infection significantly suppresses the expression of the m6A reader protein YTHDF1 in gastric cancer cell lines and patient samples." (PMID 41472023, 2025). "Acetylation of SRSF2 by LLPS upregulates YTHDF1 expression and promotes gastric cancer cell proliferation and migration." (PMID 40211955, 2025). "Engineered small extracellular vesicles were used to effectively deliver short interfering RNA targeting YTHDF1, leading to efficient depletion of YTHDF1 expression in gastric cancer tissues." (PMID 38856795, 2024).
gastric cancer (continued). "In this study, we aim to probe the role of YTHDF1 in environmental carcinogen‐induced malignant transformation of gastric cells and gastric cancer (GC) carcinogenesis." (PMID 38444279, 2024). "LINC00337 acts as an oncogenic lncRNA via its effect on EZH2, to repress p21 and promote gastric cancer cell proliferation, and through the miR-1285/YTHDF1 axis, to promote the progression of lung adenocarcinoma." (PMID 38279317, 2024). "Consequently, H19 plays a regulatory role in gastric cancer (GC) angiogenesis through the YTHDF1/SCARB1 axis, offering additional insights into the mechanism underlying HIF‐1α/H19/YTHDF1/SCARB1 regulation in GC angiogenesis." (PMID 39135292, 2024). "YTHDF1 has been found to be overexpressed in gastric cancer (GC) and has been identified as an oncogene because of its induction of cell proliferation, and it has also been found to be associated with the antitumor immune response." (PMID 37485079, 2023). "YTHDF1 has been demonstrated to promote the metastasis of gastric cancer in an m6A-dependent way by promoting USP14 translation." (PMID 38042806, 2023). "KIAA1429 promotes cell proliferation and enhances the resistance of gastric cancer cells to cisplatin by increasing FOXM1 expression via YTHDF1." (PMID 36835633, 2023). "The knockout of YTHDF1 also significantly decreased gastric cancer cell proliferation and tumorigenesis in vivo." (PMID 36835655, 2023). "Mechanistically, KIAA1429 regulated the sensitivity of gastric cancer cells to cisplatin by stabilizing FOXM1 mRNA via YTHDF1." (PMID 36291811, 2022). "For example, in gastric cancer progression, mutated YTHDF1 enhances the expression of the key oncogenic factor Wnt receptor Frizzled7 (FZD7), leading to gastric cancer progression and poor prognosis." (PMID 35707365, 2022). "In gastric cancer, GDF-15 can be used as a biomarker for gastric cancer; In liver cancer, YTHDF1 expression is elevated in liver cancer patients; In UCEC, Li found that Mammaglobin B is a prognostic marker of UCEC." (PMID 34670872, 2021). "YTHDF1 and its m6A-mediated regulation of Wnt/β-catenin signaling promote gastric cancer progression." (PMID 34277622, 2021). "In gastric cancer (GC), YTHDF1 is overexpressed and correlates with poor prognosis." (PMID 41403953, 2025). "Furthermore, N-acetyltransferase 10 (NAT10) interacts with YTHDF1 pre-mRNA, thereby inducing elevated skipping of YTHDF1 exon 4 that can stimulate gastric cancer cell proliferation." (PMID 40986143, 2025). "For instance, YTHDF1 affects translation of Frizzled7 in an m6A-dependent manner in gastric cancer." (PMID 37259333, 2023). "However, in gastric cancer, highly expressed YTHDF1 inhibits the immune microenvironment of gastric cancer by inducing the proliferation of tumor cells and inhibiting the infiltration of dendritic cells." (PMID 36618420, 2022). "Therefore, detecting the level of m6A-methylated reading protein YTHDF1 in gastric cancer tissues after treatment can serve as an indicator to predict the prognosis of patients." (PMID 36561529, 2022). "In gastric cancer, YTHDF1 recognized m6A modified SPHK2 mRNA that was catalyzed by METTL3." (PMID 36291811, 2022). "Suppression of YTHDF1 inhibited the proliferation and tumorigenesis of gastric cancer cells." (PMID 33928028, 2021). "Transcript levels of IFN-α, IFN-β, and IFN-γ were observed to be downregulated after knockdown of METTL14/YTHDF1 in gastric cancer cell lines, while IFN-α and IFN-β were involved in promoting the accumulation of pDCs in TME and the expression of PD-L1 in CD4+CD25+Tregs." (PMID 34858499, 2021). "For example, YTHDF1, YTHDF2, and especially METTL3 are associated with gastric cancer." (PMID 34277622, 2021).
gastric cancer (continued). "The C‐terminal intrinsically disrupt the region of NAT10 to alter the liquid–liquid phase separation (LLPS) and regulate m6A reader YTH N6‐methyladenosine RNA binding protein 1 (YTHDF1) splicing thereby promoting gastric cancer (GC) progression." (PMID 39640362, 2024). "YTHDF1 was proved to be high expressed in gastric cancer (GC) and worked as an independent prognosis biomarker of poor survival for GC patients." (PMID 36707507, 2023). "In this study, we investigated how EBV infection alters the m6A methylation pattern in gastric cancer cells and examined its impact on TSC22D1 mRNA stability through interaction with the m6A reader protein YTHDF1." (PMID 41472023, 2025). "The regulatory axis between YTHDF1 and TSC22D1 highlights a previously unrecognized mechanism through which EBV promotes gastric cancer progression." (PMID 41472023, 2025). "For example, YTHDF1 helps translate ubiquitin-specific peptidase (USP14) through an m6A-dependent pathway, activating the AKT/ERK pathway, which boosts the growth of gastric cancer cells and their resistance to cisplatin." (PMID 41584846, 2025). "In gastric cancer, NAT10-mediated SRSF2 stabilization induces exon skipping in YTHDF1 pre-mRNA, creating a truncated m6 A reader isoform that promotes tumor progression." (PMID 40588654, 2025). "To assess the effect of YTHDF1 on the tumorigenic properties, we generated a YTHDF1 overexpression vector and introduced it into two EBV-positive gastric cancer cell lines." (PMID 41472023, 2025). "One study showed that H19 effectively recruited the m6A reader YTHDF1, which significantly promoted the translation of SCARB1 and facilitated angiogenesis, specifically in gastric cancer." (PMID 38965575, 2024). "For instance, elevated levels of YTHDF1 and YTHDC2 are adverse prognostic factors for gastric cancer (GC), while increased IGF2BP3 levels are adverse prognostic factors for bladder cancer." (PMID 39062595, 2024). "YTHDF1 can act as an oncogene in gastric cancer (GC), while the biological mechanisms via which YTHDF1 regulates gastric tumorigenesis through m6A modification remain largely unknown." (PMID 33791305, 2021). "YTHDF1 expression could inhibit gastric tumorigenesis by altering the translation of a key WNT receptor frizzled 7 (FZD7) in an m6A-dependent manner and regulating WNT/β-catenin signaling in gastric cancer." (PMID 39009956, 2024). "Knockdown of METTL14 and YTHDF1 could reduce mRNA transcript levels of interferon signaling IFNA/IFNB/IFNG/ISG5, which is involved in the formation of the gastric cancer (GC) microenvironment and suppresses the antitumor immunity mediated by interferon signaling blocking." (PMID 36226062, 2022). "Previous studies have reported that YTHDF1 promotes the occurrence and metastasis of gastric cancer in an m6A-dependent manner by promoting the translation of USP14 and it may represent a potential target for gastric cancer treatment." (PMID 34677810, 2021).
lung cancer (40 papers, 2019 to 2025). A malignant neoplasm involving the lung. "This study focuses on elucidating the function of YTHDF1 in the development of lung cancer and its underlying mechanism." (PMID 37259333, 2023). "YTHDF1 expression may be linked to the prognosis of lung cancer, as indicated by data from the TCGA and GEO databases." (PMID 40278596, 2025). "As we expected, the preliminary experiments illustrated that the loss of YTHDF1 significantly inhibited lung cancer cell proliferation, migration and invasion, implying that it may act as an oncogene in the pathogenesis of lung cancer." (PMID 37259333, 2023). "We demonstrated that YTHDF1 was highly expressed in lung carcinoma progression; then, the loss of function experiments in lung cell lines confirmed that knockdown of YTHDF1 suppressed cell proliferation, migration and invasion and induced ferroptosis of lung cancer cells." (PMID 37259333, 2023). "YTHDF1 has also been implicated in hypoxia and oxidative stress examined in lung cancer studies." (PMID 33616673, 2021). "The exact molecular mechanisms through which YTHDF1, acting as an m6A reader, regulates lung cancer initiation and progression have yet to be fully elucidated." (PMID 40278596, 2025). "YTHDF1 (YTH domain family member 1‌) accelerates ferritin translation in a m6A-dependent manner and reduces the susceptibility of lung cancer cells to ferroptosis." (PMID 39875356, 2025). "Based on previous studies, YTHDF1 has been shown to facilitate the proliferation of lung cancer, endometrial cancer, and other types of cancers." (PMID 39821576, 2025). "Although some studies have investigated the pathogenic mechanism of YTHDF1 in lung cancer, the progression of lung cancer results from the mutual regulation of multiple factors, with fewer studies conducted to investigate the regulatory axis of YTHDF1." (PMID 40278596, 2025). "In conclusion, miR-139-5p promotes lung cancer cell growth through the direct regulation of YTHDF1 mRNA." (PMID 40278596, 2025). "Recently, a seven-gene m6A/m5C risk model, comprising METTL3, NPLOC4, RBM15, YTHDF1, IGF2BP1, NSUN3, and NSUN7, was developed to stratify the prognosis of early-stage lung cancer." (PMID 40279954, 2025). "PCR and Western blot experiments on HBE, HBE-P35, and A549 cells demonstrated that the expression of YTHDF1 was higher in malignant transformed and lung cancer cells compared to HBE cells." (PMID 40278596, 2025). "This research explored how YTHDF1 regulates both malignantly transformed bronchial epithelial cells and A549 lung cancer cells." (PMID 40278596, 2025). "Immunohistochemical staining (IHC) experiments on clinical lung cancer tissues using tissue microarrays demonstrated a positive correlation between YTHDF1 and its downstream proteins, CDK6 and MAP3K6." (PMID 40278596, 2025). "Subsequent experiments involving the immunohistochemical staining of clinical lung cancer tissue microarrays and detection of YTHDF1 expression levels in HBE-P35 and A549 cells further confirmed this trend." (PMID 40278596, 2025). "A previous study found that METTL3 promotes the FTH m6A methylation and enhances its mRNA stability in a YTHDF1-dependent manner, with YTHDF1 inhibiting ferroptosis by upregulating FTH in lung cancer." (PMID 38392340, 2024).
lung cancer (continued). "SH3BP5 was identified as a downstream target of METTL3 that inhibited lung cancer invasion through regulating SH3BP5 mRNA stability in a YTHDF1-dependent manner." (PMID 39135791, 2024). "This study revealed that m6A‐related genes significantly contribute to lung cancer, with the expression levels of YTHDF1, YTHDF2, ELAVL1 and ZC3H13 being crucial for predicting and treating lung cancer, providing new therapeutic targets." (PMID 39135292, 2024). "For example, ZC3H13, CBLL1, ELAVL1, and YTHDF1 are differentially expressed in lung cancer tissues, which is significant for predicting and treating lung cancer." (PMID 37938417, 2023). "In non–small cell lung cancer, YTHDF1 upregulates the translation efficiency of CDK2, CDK4, and cyclin D1, and YTHDF1 is also elevated in people who live at high altitudes, possibly through the hypoxia Keap1–Nrf2–AKR1C1 pathway." (PMID 37086786, 2023). "In our research, we found that the expression of the m6A reader enzyme YTHDF1 in lung cancer was highly upregulated." (PMID 37259333, 2023). "We discovered that, in lung cancer cells, YTHDF1 depletion results in intracellular Fe2+ level increasing and iron accumulation, which causes ROS production and induces ferroptosis at last." (PMID 37259333, 2023). "All of these results verified that YTHDF1 promotes lung cancer cell proliferation, migration and invasion by regulating FTH." (PMID 37259333, 2023). "All in all, these data suggested that YTHDF1 promotes lung cancer cell proliferation, migration and invasion in vitro and plays an oncogenic role in lung carcinoma." (PMID 37259333, 2023). "In our present study, we identified that YTHDF1 played a significant role in lung adenocarcinoma occurrence and metastasis, and YTHDF1 can be regarded as a predictable factor in lung cancer." (PMID 37259333, 2023). "Collectively, our data suggested that the upregulation of YTHDF1 promotes lung cancer carcinogenesis by accelerating ferritin translation in an m6A-dependent manner." (PMID 37259333, 2023). "In order to explore the biological role of YTHDF1 in lung cancer, YTHDF1 was knocked down in human lung adenocarcinoma cell lines." (PMID 37259333, 2023). "Further examination showed that FTH overexpression was sufficient to rescue the inhibitory effect of YTHDF1 knockdown on lung cancer cells." (PMID 37259333, 2023). "YTHDF1 promotes lung cancer progression through its involvement in the m6A demethylase ALKBH5 pathway." (PMID 36733344, 2023). "Further functional assays showed that ferritin (FTH) was identified as the key target of YTHDF1 in lung cancer cells." (PMID 37259333, 2023). "Then, we focused on the role of YTHDF1 in lung cancer cells and revealed the potential mechanism involved in this pathological process." (PMID 37259333, 2023). "To further clarify the molecular mechanism of the m6A regulator YTHDF1, consistent with ferroptosis in lung carcinoma, we assessed intracellular Fe2+, intracellular ROS and lipid peroxidation levels in H1299 and A549 cells." (PMID 37259333, 2023). "To evaluate the expression profile of m6A readers in lung cancer, we analyzed known readers, including YTHDF1/2/3, YTHDC1/2, HNRNPA2B1, HNRNPC/G, eIF3A, FMR1 and IGF2BP1/2, in LUAD and lung squamous cell carcinoma (LUSC) via the GEPIA database." (PMID 33232910, 2021).